BDNF (brain derived neurotrophic factor)
Diseases named in the same sentence as BDNF in open-access papers (continued):
Sharing a sentence is not in itself a finding about the gene and the disease.
depression (continued). "Furthermore, this review discusses explicitly the regulation of BDNF by acupuncture in several nervous system diseases, including neuropathic pain, Parkinson’s disease, cerebral ischemia, depression, spinal cord injury, and other diseases." (PMID 37780709, 2023). "The interplay between BDNF and oxidative stress in depression is sustained by several studies." (PMID 37631295, 2023). "Reduced levels of BDNF induce Hip atrophy and reduction in Hip volume in patients with depression." (PMID 36639604, 2023). "Some studies investigated the three–way interaction model of BDNF Val66Met polymorphism, the serotonin transporter linked promoter region (5-HTTLPR) polymorphism, and childhood adversity in predicting the development of depression." (PMID 34590201, 2023). "Moreover, chronic treatment with BER attenuated depression in mice, which was mediated by up-regulation of BDNF expression in the hippocampus." (PMID 36594063, 2023). "Notwithstanding some differences across studies, we hypothesize that different forms of depression, primarily in drug-free patents, may present with a similar degree of low plasma BDNF compared to healthy individuals." (PMID 37759825, 2023). "Another biomarker that could be considered a promising indicator of depression state and recovery is serum BDNF level." (PMID 34590201, 2023). "Hence, BDNF upregulation in the brain is considered beneficial for preventing and treating depression." (PMID 38082356, 2023). "The expression of BDNF was found to be decreased in the hippocampus of patients with depression and the upregulation of BDNF might be used in the antidepressant treatment." (PMID 37033659, 2023). "Furthermore, several studies indicate towards a reduced BDNF signaling in depression and improvement with the antidepressant drug treatment." (PMID 37490224, 2023). "The improvement of depression by EA may be achieved by activating the tissue plasminogen activator (tPA)/BDNF/TrkB pathway." (PMID 37735698, 2023). "Additionally, the results revealed that in depression, an increase in mir-132 and 124 levels are accompanied by a reduction in BDNF and GR levels, respectively." (PMID 37396946, 2023). "Furthermore, ketamine-provoked rapid antidepressant effects have been shown to largely depend on BDNF to improve synaptic impairments in depression." (PMID 37914710, 2023). "Therefore, synapses and BDNF are reduced in depression, but restoration of BDNF rescues synaptogenesis, reversing depression." (PMID 36911109, 2023). "Thus, understanding the intricate relationship between serotonin and BDNF is important for advancing our knowledge of major depression disorder." (PMID 37631295, 2023). "One of the mechanisms implicated as central to ketamine’s antidepressant mechanisms, is a rapid elevation of the growth factor brain-derived neurotrophic factor (BDNF), also implicated in the pathophysiology of depression and response to conventional antidepressants (Björkholm and Monteggia, 2016)." (PMID 37614344, 2023). "However, BDNF concentrations increase after antidepressant therapy, and there is a good correlation between BDNF changes and improvements in depression scores." (PMID 37108052, 2023). "Another study showed that the BDNF level is correlated with another depression rating score." (PMID 37396946, 2023). "Very little is known about the serum NGF and proNGF in humans, while the serum BDNF and proBDNF ratio has been investigated—, also the relationship to the psycho-cognitive parameters, in patients with major depression, obstructive sleep apnea with psoriasis, and autism." (PMID 37175781, 2023). "CUMS-induced depression-like behavior was associated with protein kinase B (AKT)/GSK-3β signaling, while swimming significantly increased CREB/BDNF and AKT/GSK-3β signaling in the hippocampus of CUMS mice, and the expression of BDNF was upregulated." (PMID 37239191, 2023).
depression (continued). "In another study, it was observed that CREB activity in the lymphocytes and BDNF level in the plasma of peripheral blood were associated with Alzheimer’s disease, meanwhile, CREB activity and BDNF level in platelets seemed to be related with to depression." (PMID 37013544, 2023). "Thus, the BDNF-MAPK-CREB cascade represents a current target for developing pharmacotherapies for depression." (PMID 36818650, 2023). "It has been shown that alterations in BDNF expression could play a role in the development of epilepsy as well as psychiatric disorders, such as bipolar disorder and depression." (PMID 37252132, 2023). "Stress and depression decrease BDNF expression and function in these two areas." (PMID 38067664, 2023). "Apigenin potentiates the neurotrophic activities of BDNF through direct binding, which may serve as a possible treatment for its curative efficiency in neurodegenerative diseases and depression." (PMID 37101380, 2023). "This SNP is not directly associated with depression, but the BDNF gene polymorphism has been shown to increase vulnerability to develop depression for individuals exposed to early life stress or trauma." (PMID 37614344, 2023). "The mechanism by which iron induces depression is unclear, although it may be partially related to the level of BDNF and oxidative stress." (PMID 37108261, 2023). "BDNF play an important role in the pathophysiology of major depression (MD)." (PMID 36831119, 2023). "Moreover, the brain-derived neurotrophic factors (BDNF) which regulate the synaptic plasticity have a major role in the pathophysiology of depression and the effect of antidepressant treatments." (PMID 36517694, 2023). "Brain-derived neurotrophic factor (BDNF) exhibits a significant pathophysiological role in depression, and it has been suggested that BDNF might enhance seizure susceptibility by inducing the synaptic plasticity." (PMID 37006477, 2023). "It is well known that BDNF plays important roles in neurogenesis and depression." (PMID 37937262, 2023). "Meta-analyses revealed altered BDNF levels in neurologic disorders, including Parkinson’s disease, Alzheimer’s disease, and psychiatric disorders, including autism, depression, post-traumatic stress disorder, and anxiety disorder, compared with normal controls." (PMID 36787304, 2023). "On the other hand, low levels of BDNF may exacerbate oxidative stress by impairing the brain’s antioxidant defenses, influencing each other in the context of depression and other neuropsychiatric diseases such as bipolar disorder." (PMID 37631295, 2023). "The present study suggests BDNF Val66Met gene polymorphism plays a role in major depressive disorder in Caucasian populations but no such pattern was found in Asian populations." (PMID 37415688, 2023). "Some studies suggest that miRNA and brain-derived neurotrophic factor (BDNF) may be involved in the process of depression in combination with essential hypertension." (PMID 38084332, 2023). "On the other hand, another study showed that the modulation of hippocampal BDNF with vitamin D might be an effective prevention strategy against depression in animal models of depression." (PMID 37762245, 2023). "Additionally, the administration of ADs augments BDNF brain levels, supporting the pathogenetic role of reduced BDNF in depression." (PMID 37511930, 2023). "The molecular mechanisms of BDNF contribution in the pathophysiology of PD depression remain largely unknown." (PMID 37374342, 2023). "Since it is estimated that up to 63% of OSA patients might suffer from this illness, BDNF alterations could influence the course of depression in this group." (PMID 36768132, 2023). "However, a decrease in the expression level of BDNF in patients with depression was generally accompanied by increased SERT." (PMID 37396946, 2023).
depression (continued). "Studies demonstrate the beneficial effects of intermittent hypoxia on neurological disorders, including depression, by promoting neurogenesis via BDNF signaling; however, the mechanisms are not fully explored as for the potential beneficial effects through the HIF-1 hypoxia responding factor." (PMID 37008780, 2023). "The potential of BDNF-related treatments for various conditions including depression is promising, but there are some weaknesses that warrant consideration and further research, such as limited efficacy mainly due to delivery and central availability issues and safety concerns." (PMID 37631295, 2023). "Since bipolar and major depressive disorders indicate reduced PFCs' BDNF expression and other neurotrophic factors, antidepressant mechanism might involve elevating BDNF expression." (PMID 37799103, 2023). "Studies have shown that reduced BDNF in the HP can induce depressive-like behavior and impair neuronal differentiation in the HP, supporting the neurotrophic hypothesis of depression." (PMID 37836833, 2023). "It is noteworthy, however, that the cellular and molecular underpinnings of BDNF’s involvement in the response to stress in animal models and the origin and development of depression remain unclear." (PMID 37298449, 2023). "Our results corroborate a large body of evidence in the literature, which shows that BDNF peripheral levels increase with physical exercise in healthy people and in those with comorbidities such as depression, cognitive impairment, anxiety and neurodegenerative diseases." (PMID 38055476, 2023). "BDNF was found to decrease in the brains of both depression patients and depressive-model animals." (PMID 38094892, 2023). "The biological factors believed to influence depression include oxidative stress, inflammation, increased cortisol production, decreased levels of brain-derived neurotrophic factor (BDNF), impaired mitochondrial ATP production, and microbiota through shifts in the metabolites released." (PMID 38260072, 2023). "Methylation analyses of 9 promoter/regulatory regions of genes known to be implicated in depression/PTSD (ADCYAP1, BDNF, CRHR1, DRD2, IGF2, LSD1/KDM1A, NR3C1, OXTR, SLC6A4) were performed on DNA from blood samples by the MassARRAY EpiTYPER platform, with MassCleave settings." (PMID 36001138, 2023). "Three studies measured BDNF levels in patients with DM and depression vs. controls." (PMID 36787304, 2023). "BDNF is one of the most investigated genes regarding depression and AD response." (PMID 37047730, 2023). "A systematic review of eight studies (n = 684) provides data that BDNF dysregulation could play a role in depression, though more research is needed to provide additional evidence that decreased BDNF levels are consistently seen in a completed suicide." (PMID 37242525, 2023). "The aim of this study is to examine the factors that contribute to anxiety and depression in individuals undergoing maintenance hemodialysis (MHD), as well as their association with serum levels of brain-derived neurotrophic factor (BDNF), neurotrophin-3 (NT-3), and serotonin (5-HT)." (PMID 37750080, 2023). "Furthermore, meta-analyses have shown that BDNF levels change in neurological illnesses such as Parkinson’s disease and Alzheimer’s disease, as well as in psychiatric disorders such as autism, depression, post-traumatic stress disorder, and anxiety disorders." (PMID 38001940, 2023). "BDNF has been involved in the neurobiology of both depression and PD." (PMID 37374342, 2023). "BDNF plays an important role in promoting the growth and differentiation of immature metagenesis, the survival and maintenance of mature neurons, and improving neuroplasticity and antidepressant treatment during the occurrence of depression." (PMID 37118929, 2023).
depression (continued). "In a clinical controlled trial, Xue found that the BDNF level of perimenopausal depression patients who took venlafaxine capsule increased, the HAMD score and depression symptoms improved significantly, and the good or bad drug effect was related to the BDNF level." (PMID 37065890, 2023). "Indeed, this compound has reported antioxidant properties and improved depression-like behavior, activating BDNF signaling and, thus, modulating neurogenesis and neuroplasticity." (PMID 36830028, 2023). "Furthermore, in terms of genetic abnormalities, there are also links between genetic factors and depression; for example, abnormalities in brain-derived neurotrophic factor (BDNF) appear to play an important role in depression." (PMID 36902200, 2023). "Therefore, XPJYF treatment possibly regulated BDNF expression in astrocyte to function as the anti‐inflammation and anti‐depression effects." (PMID 36550591, 2023). "Likewise, the most repeatedly validated biomarkers of depression include hypercortisolemia, hypocholesterolemia, reduced brain-derived neurotrophic factor, and increased interleukin 6 (Caruncho and Rivera-Baltanás, 2010)." (PMID 37645061, 2023). "A deficiency of BDNF or Trk receptors does not induce depression, but antidepressants are required to increase BDNF activity and restore neuronal networks." (PMID 37108261, 2023). "However, investigations on epigenetic changes in BDNF have been described in individuals with psychiatric disorders and neurodegenerative diseases, including depression, Huntington's disease, and schizophrenia." (PMID 37008217, 2023). "Therefore, depressive behavior tests and depression-related factors such as ACTH, CORT, NE, 5-HT, and BDNF were usually used to evaluate the depression mice model." (PMID 38088959, 2023). "Brain-derived neurotrophic factor (BDNF) has been suggested as a reliable biomarker for depression and a strong predictor of CVD because it plays an important role in neuron survival and growth, serves as a neurotransmitter modulator, and promotes neuronal plasticity." (PMID 37895349, 2023). "The aim of this review was to explore the relevant neurobiology and the association between peripheral levels of brain-derived neurotrophic factor (BDNF) and acute and short to long-term exercise regimes, as well as its relation to depression and antidepressant treatment." (PMID 36969600, 2023). "According to the neurotrophic hypothesis, reduced BDNF expression leads to neuronal atrophy, diminished synaptic plasticity, and contributes to the pathogenesis of depression." (PMID 38152691, 2023). "Additionally, the presence of “MicroRNA” (160 occurrences) and “BDNF” (114 occurrences) signifies considerable interest among researchers in the context of epigenetic studies related to depression." (PMID 38249586, 2023). "Studies have shown that individuals with depression exhibit reduced levels of BDNF in the brain." (PMID 37492530, 2023). "Similar to other adaptogens, it has been proposed that Rhodiola rosea might alleviate depression via the BDNF/TrkB-GSK-3β signaling pathway." (PMID 37047914, 2023). "In support to our findings, DMF boosted the level of BDNF in a spinal cord injury model and hypothyroid rat brain, alleviated depression-like symptoms through BDNF upregulation, and activated the TrkB/AKT/CREB trajectory in association with reduced ROS production in an AD model." (PMID 37056990, 2023). "Numerous reports using depression-like behaviors or different animal models manipulating the expression of BDNF or its receptor TrkB suggest that BDNF/TrkB participates in the pathophysiology of depression as well as the mechanism of action of antidepressant treatments." (PMID 37387537, 2023). "Tsai proposed that stimulating the production of brain-derived neurotrophic factor in the nervous system may explain the probable effect of GA on depression." (PMID 38310425, 2023).
depression (continued). "In the future, we plan to investigate whether the administration of Shiikuwasha upregulates BDNF level and induces antidepressant-like effects in a rat model of depression." (PMID 38082356, 2023). "Hence, more studies are needed to verify the role of BDNF as a biomarker in depression among children and adolescents." (PMID 34590201, 2023). "Evidence has suggested that elevated miR-199a-5p levels could regulate depression by targeting Wnt family member 2 (Wnt2) signaling to brain-derived neurotrophic factor (BDNF)." (PMID 37505566, 2023). "Through additional protein-protein interactions that recalibrate protein phosphorylation, FKBP51 also impacts signaling of other depression-relevant pathways such as GSK3β, BDNF, and nuclear factor kappa B, linking it to inflammation and the immune system, as well as autophagy." (PMID 36203007, 2023). "Iron and zinc deficiencies induce neurological and physical symptoms and psychiatric symptoms related to depression, which may be related to BDNF and oxidative stress levels." (PMID 38155897, 2023). "Interestingly, quercetin alleviates depression-like behavior by stimulating AHN via BDNF expression in mice after chronic unpredictable mild stress exposure." (PMID 37533986, 2023). "Brain-derived neurotrophic factor (BDNF), which is the most abundant neurotrophin and is involved in neuroplasticity and neurotransmission, also has an important role in the etiology and treatment of depression." (PMID 37759825, 2023). "Spearman’s correlation analysis showed that different microbial communities (Corynebacterium, Faecalibaculum, Enterorhabdus, Desulfovibrio) correlation with differential metabolites (Cholic acid, Deoxycholic acid, etc.)and depression-related biochemical indicators (5-HT, DA, BDNF, IL-6, and TNF-α)." (PMID 37692389, 2023). "The increase in BDNF and related synaptogenic factors are considered essential to ketamine’s antidepressant effects, and BDNF has been identified as a potential candidate as a biomarker of depression severity and treatment response." (PMID 37614344, 2023). "Recently, it was shown that the treatment with the probiotic Bacillus coagulans Unique IS-2® reduced chronic stress-induced depression in rats by a mechanism related to an increase in BDNF and 5-HT levels and a decrease in TNF-α, IL-1β, and dopamine levels in the hippocampus and frontal cortex." (PMID 37892186, 2023). "Interestingly, this same study unveiled an inverse correlation between BDNF levels and the severity of depression across all participants." (PMID 37892471, 2023). "Also, further research requires consideration of other mechanisms that increase the risk of depression in SDB individuals, such as brain-derived neurotrophic factor signaling pathway." (PMID 37479853, 2023). "People with depression also have lower levels of BDNF in their blood." (PMID 38067664, 2023). "NGF and BDNF are two members of the neurotrophic factor family with crucial roles in the formation and plasticity of cerebral neural networks, and they are mainly involved in the pathophysiological mechanism of depression." (PMID 37298063, 2023). "On other hand, low serum BDNF levels were observed in patients with major depression." (PMID 36767135, 2023). "Furthermore, there is a linkage between SGK-1 and BDNF, a neurotrophin that has a leading role in the etiology of depression." (PMID 38004136, 2023). "After the behavioral experiments, we examined how our results could be explained by two accepted theories of depression development: the monoamine and BDNF hypotheses." (PMID 37908978, 2023). "The results of behavioral tests and neurobiological factor detection after FMT showed that the control mice that had accepted FMT had depressive behaviors, and the hippocampus and PFC concentrations of NE, 5-HT, and BDNF had decreased in the antibiotic-induced depression mice." (PMID 38088959, 2023). "There is a growing body of evidence linking BDNF to the pathogenesis of depression." (PMID 37089558, 2023).